CACNA1A (calcium voltage-gated channel subunit alpha1 A)
Diseases named in the same sentence as CACNA1A in open-access papers (continued):
Sharing a sentence is not in itself a finding about the gene and the disease.
Ataxia (continued). "This paradox has already been described in other patients with ataxia and mutations in KIF1A, ITPR1, and PMPCA but also in KCNC3, and CACNA1A genes." (PMID 36233161, 2022). "Injected mice developed pathological features that resemble SCA6 (early-onset ataxia, motor deficits, and Purkinje cell degeneration), thus confirming the causative role of CAG repeats’ expansion in the second cistron of the CACNA1A gene." (PMID 35625877, 2022). "Since the gait disorder is the major ataxia manifestation and a major source of disability in CACNA1A patients, the definition of gait-specific, more sensitive biomarkers/outcome measures is urgently needed in the view of future clinical trials." (PMID 34755206, 2022). "Triplet repeat mutations in the CACNA1A gene were associated with late onset-spinocerebellar ataxia type 6 (MIM#183086) characterized by late onset, slowly progressive cerebellar ataxia, due to toxic accumulation of an expanded polyQ." (PMID 34068417, 2021). "In contrast to other forms of episodic ataxia associated with KCNA1 (EA1) or CACNA1A (EA2), ataxia occurred after minor head trauma and acute cerebellar diffusion restriction together with late T2-hyperintensities was visible on MRI." (PMID 33126500, 2020). "The genetic complexity and the overlapping phenotypes of ataxias led our group to screen the CACNA1A gene in 31 cases that were clinically diagnosed with suspected EA2 and were referred to our laboratory for genetic testing." (PMID 32466254, 2020). "Hypoglycosylation of both CaV2.1 subunits (α1A and α2α) induced gain-of-function effects on channel gating that mirrored those reported for pathogenic CACNA1A mutations linked to FHM and ataxia." (PMID 29470411, 2018). "Five patients with CACNA1A mutation (patients 1, 2, 3, 4, and 5) revealed typical clinical features of EA2 including early age of onset, a positive family history, recurrent ataxia for several hours, interictal nystagmus, and response to acetazolamide." (PMID 29062094, 2017). "The link with various forms of ataxia and mutations in CACNA1A is rather complex, suggesting that neuronal calcium influx through CaV2.1 channels is tightly controlled." (PMID 28900389, 2017). "Here, we investigated the effect of the treatment with Acetyl-DL-leucine on the walking stability of patients with cerebellar ataxia (10x SAOA, 2x MSA-C, 2x ADA, 1x CACNA-1A mutation, 2x SCA 2, 1x SCA 1)." (PMID 27073690, 2016). "Accordingly, mutations in the CACNA1A gene are linked to familial and sporadic hemiplegic migraine (FHM/SHM), and both episodic and progressive forms of ataxia." (PMID 26716990, 2015). "Mutations in two subunits of Cav2.1 in mice, CACNA1A (AAW56205.1) and CACNA2D2 (Q6PHS9.1), also exhibit ataxia, epilepsy and neurodegeneration." (PMID 25811491, 2015). "Multiple dominant gain and loss of function mutations in CACNA1A have been described in patients, resulting in a spectrum of disorders: in particular, familial hemiplegic migraine (FHM)-1, Episodic ataxia (EA)-2, spinocerebellar ataxia (SCA)-6, and epilepsy." (PMID 26386135, 2015). "All of the homozygous recessive Cacna1a mice developed ataxia, ranging from mild in the rocker, tottering, and rolling Nagoya mice to severe ataxia in the leaner mice." (PMID 22952933, 2012). "An example is mutations in the CACNA1A gene, which causes familial hemiplegic migraine (FHM-1), episodic ataxia (EA-2) or spinocerebellar ataxia (SCA-6)." (PMID 20385006, 2010). "CACNA1A-associated disease was the most frequent etiology in a large global cohort of patient with cerebellar ataxias due to non-expansion variants and is increasingly recognized in the setting of manifold neurological phenotypes." (PMID 41240219, 2025). "CACNA1A, linked to SCA6, has been described in cases of parkinsonism combined with cerebellar ataxia, with both L-dopa-responsive and non-responsive presentations, suggesting variability in dopaminergic dysfunction." (PMID 41009775, 2025).
Ataxia (continued). "Loss-of-function mutations in the human CaV2.1 subunit-encoding CACNA1A gene are linked to the autosomal dominant cerebellar disease episodic ataxia type 2 (EA2), manifesting as paroxysmal attacks of ataxia and nystagmus." (PMID 39609819, 2024). "The role of the calcium channels in cerebellar pathways has been widely described as well as it is commonly agreed the association between calcium channelopathies, mainly N and T calcium channels (respectively encoded by the genes CACNA1A and CACNA1G-H-I), and cerebellar ataxia." (PMID 38790536, 2024). "Additionally, a mouse knockout study reported that CACNA1A knockout results in ataxia and death through the removal of channel-mediated neurotransmission." (PMID 37510383, 2023). "In other extreme examples, patients with mutations in CACNA1A, ATP1A2, or SCN1A had attacks more often, may be triggered by mild head trauma and were associated with extensive motor weakness, ataxia, confusion, and brain edema." (PMID 35910262, 2022). "This is also supported by the finding that R1664Q located in the homologous position in CACNA1A also causes an early-onset and progressive form of ataxia not characterized by the typical episodic features of EA-2." (PMID 33746731, 2021). "To explore the potential contribution of the genetic variation to the ataxia phenotype in the ion channel genes, we also analyzed 353 ion channel genes (Tier-2) in the 16 EA patients who tested negative for CACNA1A mutations." (PMID 32466254, 2020). "Changes in CF pause durations are a common finding in mouse models for ataxia and hemiplegic migraine, for example in a migraine mouse model carrying a mutation in Cacna1a or in ataxic mice lacking BK channels." (PMID 32954283, 2020). "Similarly, conditional ablation of Cav2.1 channels leading to Cacna1a gene LOF in mice resulted in ataxia and dystonia starting at around postnatal days 10–12 and death at postnatal days 21–22." (PMID 31875924, 2020). "A severe epileptic phenotype was also present in two siblings with a heterozygous compound CACNA1A mutation (a missense and a 7 amino acid frameshift deletion), whose heterozygous relatives had only mild intellectual deficit, but no episodes of ataxia." (PMID 32899446, 2020). "Interestingly, some clinical, neuroimaging and neurophysiological features of PMM2-CDG patients and CACNA1A mutated patients are similar, including not only SLE, but also ataxia, ocular motor disturbances, and cerebellar atrophy on MRI." (PMID 29470411, 2018). "SCA6, the third disorder associated with mutations in the CACNA1A gene, is characterized by cerebellar ataxia and progressive cerebellar degeneration, and is caused by CAG repeat expansions in the CACNA1A gene, resulting in an aberrant polyglutamine chain in the C-terminus of Cav2.1 channels." (PMID 30279196, 2018). "In this study, we conducted next-generation sequencing in Korean EA patients to identify pathogenic mutations of five known EA genes (KCNA1, CACNA1A, CACNB4, SLC1A3, and UBR4), and explored candidate genes that cause EA as a secondary phenotype or cerebellar ataxia." (PMID 29062094, 2017). "We have expanded the functional network of genes involved in neurodegeneration leading to cerebellar ataxia related to unc-2/CACNA1A, further confirming the involvement of the transforming growth factor β pathway and adding a novel signaling cascade, the Notch pathway." (PMID 27005779, 2016). "SCA6 is from a CAG expansion in the CACNA1A gene generally manifests in the form of pure ataxia." (PMID 25866756, 2015). "Because there are no hot mutation sites for large gene like CACNA1A and overlapping clinical features among different types of ataxia, we explored next generation sequencing technology to identify mutations in all exons of four known EAs genes, KCNA1, CACNA1A, CACNB4, and SLCIA3." (PMID 23441182, 2013).
Ataxia (continued). "This is partly due to the fact that global ablation of CaV2.1 channels by Cacna1a gene deletion in a gene targeting knock-out strategy produces mutant mice with progressive neurological deficits that result in ataxia and dystonia, and that limits survival 3 to 4 weeks after birth." (PMID 24205277, 2013). "Mutations in CACNA1A (MIM 601011), encoding the transmembrane pore-forming subunit CaV2.1 of Voltage Dependent Calcium Channels (VDCCs), have been associated to the peculiar phenotypic combination of absence epilepsy and cerebellar ataxia." (PMID 24358150, 2013). "The rocker mice exhibited the mildest ataxia of the homozygous recessive Cacna1a mutants." (PMID 22952933, 2012). "Of the 4 different disease loci for which we have obtained coverage with ≥4 ESTs - spinocerebellar ataxia 6 (CACNA1A or SCA6), dentarubro-pallidolusyan atrophy, Huntington's disease and spinocerebellar ataxia 7 (SCA7) - we detected repeat size polymorphic variants for the first two." (PMID 16640792, 2006). "However, CACNA1A variants emerged as the most common monogenic etiology in a large global cohort of patients with cerebellar ataxias due to non-expansion variants." (PMID 41240219, 2025). "Mendelian diseases have been studied in the spectrum of protein–protein interactions, with a study on the two ataxia disease-causing genes ATXN7 and CACNA1A that identified new protein partners that may explain comorbidity of ataxia with other genetic diseases such as macular degeneration." (PMID 37298131, 2023). "Moreover, cerebellar atrophy was found both in patients with ataxia and in those with no clinical cerebellar signs; in these cases, a mutation of the CACNA1A gene was detected." (PMID 37297978, 2023). "This may be why KCNA1 and CACNA1A are more likely to present with ataxia than GLUT-1." (PMID 37008993, 2023). "Interestingly, chronically speaking, clinical, neuroimaging, and neurophysiological features of PMM2-CDG and CACNA1A related phenotypes are also similar, including, ataxia, ocular motor disturbances (particularly nystagmus and tonic upgaze deviation), and progressive cerebellar atrophy." (PMID 34708008, 2021). "Additionally, CACNA1A mutations have been detected in rodents and humans suffering from absence seizures with/without cerebellar ataxia." (PMID 31875924, 2020). "Normal CAG repeat length in the CACNA1A gene is up to 18 repeats, whereas individuals with 20 or more CAG repeats will develop ataxia symptoms during a normal lifespan." (PMID 38217689, 2024). "This review delves into the significance of the CACNA genes, including CACNA1A, CACNA1B, CACNA1C, CACNA1D, CACNA1E, CACNA1G, and CACNA1H, in the pathogenesis of conditions such as migraine, epilepsy, cerebellar ataxia, dystonia, and cerebellar atrophy." (PMID 38785745, 2024). "Patients affected with SCA6 have 20-33 CAG repeats in the CACNA1A gene, with slowly progressive and late-onset ataxia symptoms." (PMID 37374132, 2023). "For ataxias SCA1, SCA2, SCA3, SCA6, SCA7, SCA17 and dentatorubral-pallidoluysian atrophy, expansion beyond 39, 33, 45, 20, 34, 41, and 35 repeats in the ATXN1, ATXN2, ATXN3, CACNA1A, ATXN7, TBP, and ATN1 genes, respectively, will cause disease." (PMID 35592702, 2022). "A similar genetic alteration could also be observed in patients with ataxia and Familial Hemiplegic Migraine (FMH), the paroxysmal neurological disorder connected with mutations in ion transporters: CACNA1A that encodes the alpha 1A subunit of CaV2.1 voltage-gated channel." (PMID 36295831, 2022). "Natural history data on ataxia progression are available for SCA6, but still lack in other CACNA1A disorders." (PMID 34755206, 2022). "The frequency is followed by ATXN7: 6.09%, TBP: 5.59%, ATXN2: 5.03%, CACNA1A: 4.28%, PPP2R2B: 2.68%, and ATXN3: 2.42% with respective cutoff values in uncharacterized ataxia cases." (PMID 36618024, 2022). "The patients with CACNA1A mutations may present epilepsy without ataxia or migraine." (PMID 35600082, 2022).
Ataxia (continued). "This mutation has not been reported previously and is likely the cause of her paroxysmal dystonia; dystonia is sometimes seen during episodes of ataxia in EA2, and CACNA1A knockout mice exhibit dystonia and cerebellar atrophy." (PMID 34395002, 2021). "Moreover, there are several reports where mutations in the CaV2.1 gene (CACNA1A) cause several autosomal-dominant neurological disorders including familial hemiplegic migraine type 1, and cerebellar pathologies such as ataxia, progressive ataxia and early-onset cerebellar syndrome." (PMID 33557884, 2021). "We collected single EEG recordings from 29 adult subjects with cerebellar ataxia due to non-expansion CACNA1A disease and from 15 subjects with GAA-FGF14-related ataxia." (PMID 41240219, 2025). "Furthermore, in SCA6, an miRNA targeting the CACNA1A IRES, a newly recognized internal ribosomal entry site within the CACNA1A C-terminal coding region, reduced ataxia and PN degeneration in a mouse model." (PMID 38391932, 2024). "A further case with ataxia and Parkinson’s disease was identified through the UK Biobank, but in addition to the THAP11 STR expansion, they were also found to have a CAG STR expansion in CACNA1A, consistent with SCA6." (PMID 38760634, 2024). "Another study of CACNA1A carriers reported absence epilepsy in childhood followed in later life by slowly progressive ataxia without EA." (PMID 37008993, 2023). "On the other hand, some members of EA2 families with CACNA1A point mutations and no CAG expansion presented with prominent progressive ataxia reminiscent of SCA6." (PMID 32899446, 2020). "In this study, we investigated the EA2 cases (n = 16) found to be negative for exonic CACNA1A mutations in our previous study, by performing WES with subsequent comprehensive tier-targeted analysis of ataxia and ion channel genes." (PMID 32466254, 2020). "These reservations do not apply to the effects of 4-AP on the episodes of ataxia in humans with the CACNA1A channelopathy, EA-2." (PMID 23451282, 2013). "Moreover, conditional KO mouse with a postnatal deletion of CACNA1A in Purkinje cells do not initially present ataxia and absence epilepsy but instead develop them during adulthood, which propose these disorders arise from defects beginning in late infancy—an opportunity window for therapy." (PMID 37845370, 2023). "In this study, the 16 cases that were negative for pathogenic CACNA1A mutations underwent WES followed by a tiered analysis approach, which identified causal mutations in genes previously implicated in various neurological disorders with symptomatic overlap with ataxia and epilepsies." (PMID 32466254, 2020).
episodic ataxia type 2 (122 papers, 2008 to 2026). A form of hereditary episodic ataxia (EA) characterized by paroxysmal episodes of ataxia lasting hours, with interictal nystagmus and mildly progressive ataxia. "Spinocerebellar ataxia type 6 (SCA6) is one of three allelic autosomal dominant disorders due to mutations of the CACNA1A gene, located on chromosome 19p13; the other two being episodic ataxia type 2 (EA2) and familial hemiplegic migraine." (PMID 40790250, 2026). "For example, CACNA1A mutations have been classically associated with episodic ataxia type 2, familial hemiplegic migraine, and spinocerebellar ataxia, as well as epileptic encephalopathies and developmental syndromes." (PMID 40725423, 2025). "Pathogenic variants in CACNA1A have been implicated in a wide spectrum of neurological phenotypes, including episodic ataxia type 2, familial hemiplegic migraine, epileptic encephalopathy, and autism spectrum disorder." (PMID 40725423, 2025). "Case 2’s mother and sibling had the same nonsense variant in the CACNA1A gene, but they showed clinical heterogeneity with different symptoms: the mother had chronic cerebellar ataxia, Case 2 had episodic ataxia, and his sibling had absence seizures." (PMID 40149486, 2025). "Episodic ataxia, characterized by recurrent episodes of imbalance and uncoordinated movements, has been linked to CACNA1A variants, with distinct subtypes exhibiting different clinical presentations." (PMID 40111503, 2025). "In this study with a small number of cases, we observed a reduction in the number of episodic ataxias in three patients with CACNA1A variants following the addition of levetiracetam to acetazolamide." (PMID 40149486, 2025). "Some years after birth of child II-3, episodic ataxia type 2 was diagnosed in the mother and one of her brothers due to a heterozygous frameshift pathogenic variant in the CACNA1A gene [c.2602delG, p.(Ala868Profs*24)]." (PMID 39416668, 2024). "Pathogenic heterozygous variants in CACNA1A are associated with familial hemiplegic migraine, episodic ataxia type 2 and spinocerebellar ataxia type 6, and more recently, neurodevelopmental disorders." (PMID 39416668, 2024). "In one family (DYS-69), our analysis revealed a de novo pathogenic variant (NM_023035:c.2137G>A:p.A713T) in the CACNA1A gene, which is mainly associated with episodic ataxia and rarely dystonia." (PMID 38458754, 2024). "Calcium channelopathies, particularly mutations in CACNA1A, have been linked to various neurological phenotypes, including epilepsy, hemiplegic migraine, and episodic ataxia." (PMID 38689878, 2024). "CACNA1A mutations are known to underlie two CAs: episodic ataxia type 2 (EA2) and spinocerebellar ataxia type 6 (SCA6)." (PMID 38785745, 2024). "Episodic Ataxia Type 2 (EA2) is a rare neurological disorder caused by a mutation in the CACNA1A gene, encoding the P/Q-type voltage-gated Ca2+ channel important for neurotransmitter release." (PMID 37800168, 2023). "Other diseases with CACNA1A gene mutation include episodic ataxia type 2 and familial hemiplegic migraine 1; some patients with SCA6 show clinical overlap with these diseases." (PMID 36169768, 2023). "Mutations in the CACNA1A gene were found in episodic ataxia type 2 and spinocerebellar ataxia type 6 and epilepsy with genetic etiology." (PMID 37685382, 2023). "Other genetic variants in CACNA1A have previously been linked with various neurological disorders e.g. episodic ataxia type 2 and familial hemiplegic migraine." (PMID 35154276, 2022). "Type 2 episodic ataxia is a genetically inherited disease, associated CACNA1A channel changes, and is characterized by recurrent and disabling episodes of imbalance, vertigo and ataxia, that are induced by physical exertion or emotional stress." (PMID 35976301, 2022). "CACNA1A mutations are the cause of episodic ataxia type 2 (EA2), familial hemiplegic migraine (FHM), and spinocerebellar ataxia type 6 (SCA6), a CAG triplet repeat expansion disorder." (PMID 35757096, 2022).